PLCE1 (phospholipase C epsilon 1)
Diseases named in the same sentence as PLCE1 in open-access papers (continued):
Sharing a sentence is not in itself a finding about the gene and the disease.
gastric cancer (18 papers, 2012 to 2025). A primary or metastatic malignant neoplasm involving the stomach. "Meanwhile 22 variants were identified significantly associated with gastric cancer: 3 (PLCE1 rs2274223, PSCA rs2976392, MUC1 rs4072037) were high and 19 SNPs were intermediate level of summary evidence, respectively." (PMID 34491229, 2021). "Materials and Methods: The PLCE1 rs2274223 polymorphism was genotyped in 60 patients with gastric cancer and 69 control subjects using polymerase chain reaction and restriction fragment length polymorphisms (PCR-RFLP) methods." (PMID 31649800, 2019). "In this case-control study, the relationship between rs2274223 (A>G), a single nucleotide polymorphism in phospholipase C epsilon gene, (PLCE1) and gastric cancer was evaluated among Iranian patients." (PMID 31649800, 2019). "In summary, in this case-control study, we investigated the correlation between the functional rs2274223 SNP in PLCE1 gene and increased risk of gastric cancer for the first time in Iranian population." (PMID 31649800, 2019). "For example, among SNPs associated with increasing risk of gastric cancer (GC), PLCE1 rs2274223 has an OR of 1.57, and PSCA rs2294008 an OR of 1.33." (PMID 30597917, 2018). "Recently, several groups have published GWASs of gastric cancer focusing on single-nucleotide polymorphisms (SNPs), such as in a locus on chromosome 10q23 in the PLCE1 gene or in PRKAA1 at 5p13.1." (PMID 27121204, 2016). "Several genetic variants including PSCA rs2294008 C>T and rs2976392 G>A, MUC1 rs4072037 T>C, and PLCE1 rs2274223 A>G have shown significant association with stomach cancer risk in the previous genome-wide association studies (GWASs)." (PMID 25658482, 2015). "Logistic regression analysis of associations between the genotypes of PSCA, MUC1, PLCE1 and stomach cancer susceptibility in a Chinese population." (PMID 25658482, 2015). "The associations of MUC1 rs4072037 T>C and PLCE1 rs2274223 A>G with stomach cancer risk have also been replicated in different ethnicities." (PMID 25658482, 2015). "Stratification analysis of PSCA rs2294008 C>T, PLCE1 rs2274223 A>G and risk genotypes with stomach cancer susceptibility." (PMID 25658482, 2015). "Recently, another study found that PLCE1 rs2274223 was associated with survival following a gastric cancer diagnosis." (PMID 23826241, 2013). "Odds ratios (OR) with 95% confidence intervals (CI) were employed to assess the association of the PLCE1 rs2274223 polymorphism with a susceptibility to ESCC or gastric cancer." (PMID 23826241, 2013). "It appears that although PLCE1 rs2274223 was associated with a high risk of gastric cancer, carriers of this genotypealso had a long survival." (PMID 23826241, 2013). "In conclusion, in this case-control study of gastric cancer in an eastern Chinese population, we provided statistical evidence that confirmed the associations between the reported PLCE1 rs2274223, as well as the novel rs11187870, and risk of gastric cancer." (PMID 22412849, 2012). "Recently, two single nucleotide polymorphism (SNP) rs2274223 and rs11187870 in PLCε1 loci have been identified as novel susceptibility locus for gastric cancer in Chinese population by genome wide gene-association analysis (GWAS)." (PMID 23077637, 2012). "To date, only two recent GWASs and a replication study have investigated the association between genetic variations of PLCE1 and susceptibility to gastric cancer." (PMID 22412849, 2012). "In the present study, we confirmed the reported association between the PLCE1 rs2274223A>G SNP and gastric cancer susceptibility." (PMID 22412849, 2012). "In the combined analysis, subjects who carried more risk alleles (i.e., rs2274223G and rs11187870C) of PLCE1 showed a higher risk of gastric cancer, suggesting a joint effect of these two SNPs on gastric cancer susceptibility." (PMID 22412849, 2012).
gastric cancer (continued). "Overall, our meta‐analysis suggested that the PLCE1 rs2274223 variant might serve as a potential biological marker of esophageal and gastric cancer in East Asians." (PMID 30784231, 2019). "Our findings indicated that the PLCE1 rs2274223 variant might serve as a promising genetic biomarker of esophageal and gastric cancer in East Asians." (PMID 30784231, 2019). "With respect to the PLCE1 rs2274223 A>G polymorphism, stratification analyses observed increased stomach cancer risk with the AG/GG genotypes in younger participants, women, never smokers, never drinkers, participants with high BMI, and subjects with cardia cancer or TNM stage III+IV diseases." (PMID 25658482, 2015). "Moreover, the PLCE1 rs2274223 A>G polymorphism was found to significantly increase stomach cancer risk under the homozygous model (AG vs. AA: adjusted OR = 1.48, 95% CI = 1.15–1.90), and dominant model (AG/GG vs. AA: adjusted OR = 1.45, 95% CI = 1.14–1.84)." (PMID 25658482, 2015). "Furthermore, it was also demonstrated that PLCE1 rs2274223 was a notable signal for susceptibility to gastric cancer under the homozygous genetic model (OR = 1.52) and the heterozygous genetic model (OR = 1.29)." (PMID 23826241, 2013). "In addition, recent evidence has demonstrated that PLCE1 rs2274223 variant was associated with improved gastric cancer patient survival." (PMID 23874915, 2013). "However, the molecular mechanism underlying the biological significance of PLCε1 in gastric cancer development and progression remains obscure." (PMID 23077637, 2012). "Future studies need to address whether these factors interact with genetic variants in PLCE1 in the etiology of gastric cancer." (PMID 22412849, 2012). "In addition, the 3′ UTR rs11187870G>C SNP of PLCE1 was identified for the first time to be associated with increased risk of gastric cancer, although this SNP is in incomplete LD with rs2274223A>G." (PMID 22412849, 2012). "We then categorized the putative risk alleles of the two SNPs into the number of combined variant alleles (i.e., rs2274223G and rs11187870C) to further analyze their possible joint effect and potential locus-locus interaction of PLCE1 SNPs on risk of gastric cancer." (PMID 22412849, 2012). "Our results suggest that the function of PLCε1 protein in gastric cancer may be linked to its expression in the immune system." (PMID 23077637, 2012). "In this case-control study, we investigated the associations of two novel, potentially functional SNPs, one located in exon 26 (rs2274223A>G) and the other located in the 3′ UTR (rs11187870G>C) of PLCE1, with risk of gastric cancer in an eastern Chinese population." (PMID 22412849, 2012). "Moreover, MUC1 rs4072037 T>C may lead to splicing alteration, whereas, PLCE1 rs2274223 A>G may cause an Arg-to-His change that were significantly associated with risk of stomach cancer in the initial scanning phase." (PMID 25658482, 2015). "Therefore, we hypothesized that SNPs in the PLCE1 gene are associated with gastric cancer risk in eastern Chinese populations." (PMID 22412849, 2012). "A significant correlation was observed between three functional SNPs in PLCE1 gene (rs2274223 A>G, rs3765524 C>T and rs7922612 C>T) and gastric cancer." (PMID 31649800, 2019). "Because NCC and adenocarcinoma have been the predominant subtype of gastric cancer in China, we then examined the expression of PLCE1 in adenocarcinoma of NCC and their ANC tissues with different genotypes of rs3765524." (PMID 30931333, 2019). "In gastric cancer, several genes have been proved to be closed related to proliferation and migration of gastric cancer cells, such as Stathmin1, Id1, PLCE1." (PMID 27029190, 2016). "In the current hospital based case-control study, we investigated the potential associations of PSCA rs2294008 C>T and rs2976392 G>A, PLCE1 rs2274223 A>G and MUC1 rs4072037 T>C polymorphisms with stomach cancer susceptibility among a Chinese population." (PMID 25658482, 2015).
gastric cancer (continued). "In conclusion, this meta-analysis indicated that the PLCE1 rs2274223 polymorphism is associated with both ESCC and gastric cancer susceptibility." (PMID 23826241, 2013). "In 2010, two large-scale GWASs simultaneously reported that a new susceptibility locus (rs2274223: A5780G), located in exon 26 of PLCE1, was strongly associated with the risk of ESCC and gastric cancer in Chinese populations." (PMID 23826241, 2013). "In this study, a systematic review and meta-analysis were performed to clarify these inconsistencies and to establish a comprehensive picture of the relationship between PLCE1 gene variants and the risk of ESCC and gastric cancer." (PMID 23826241, 2013). "In this meta-analysis, the PLCE1 rs2274223 polymorphism was confirmed to have a statistically significant association with an increasing risk of ESCC and gastric cancer." (PMID 23826241, 2013). "This meta-analysis confirmed that PLCE1 rs2274223 was associated with an increase in the risks of ESCC and gastric cancer, especially gastric cardia cancer." (PMID 23826241, 2013). "These investigators examined a total of 938 gastric cancer patients and found that individuals carrying the PLCE1 rs2274223 AG/GG genotype had a higher survival rate than those carrying the AA genotype." (PMID 23826241, 2013). "The importance role of PLCε1 in gastric cancer is further highlighted by our finding of its inverse correlation with chronic atrophic gastritis." (PMID 23077637, 2012). "Simultaneously, PLCε1 protein gets higher expression in gastric cancer cells because PLCε over-expression can promote intestinal tumorigenesis in ApcMin/+ mice." (PMID 23077637, 2012). "According to these available results, we proposed a possible mechanism of PLCε1 protein functioning in tumorigenesis of gastric cancer: PLCε1 protein as an effecter of Ras and Rap small GTPases is at first expressed in normal gastric mucous tissues." (PMID 23077637, 2012). "This study was aimed to investigate the clinical significance of PLCε1 in the initiation and progression of gastric cancer." (PMID 23077637, 2012). "Compared with normal tissues, we found that PLCε1 protein was highly expressed in gastric cancer tissues, whereas it was down-regulated in atrophic gastric tissues." (PMID 23077637, 2012). "Then, we investigated the role of PLCε1 in both tumor and normal tissues in a gastric cancer tissue microarray." (PMID 23077637, 2012). "In summary, up-regulation of PLCε1 expression in gastric cancer but down-regulation in atrophic gastritis was observed by our study." (PMID 23077637, 2012). "In recent years, the PLCE1 rs2274223 polymorphism has been extensively investigated as a potential risk factor for upper gastrointestinal cancers, including squamous cell carcinoma (ESCC) and gastric cancer." (PMID 23826241, 2013). "In cardia gastric cancer, GG carriers showed a higher expression of PLCE1(1.08 fold, compared with that AA carriers; P = 0.91), while in noncardia gastric cancer, AG carriers showed a 1.52 fold higher expression of PLCE1 than that of the AA carriers (P = 0.96)." (PMID 22412849, 2012). "Our results strongly suggest that PLCε1 can be a potentially promising biomarker for distinguishing gastric cancer from atrophic gastritis and might be a potential biomarker for diagnosing early-stage gastric cancer." (PMID 23077637, 2012). "To verify whether rs2274223 would affect PLCE1 expression and thus play a role in the etiology of gastric cancer, we used the real-time PCR to measure PLCE1 expression at the mRNA level." (PMID 22412849, 2012). "Particularly, its down-regulation in inflammation environment, highly suggested that PLCε1 may be an important biomarker, and may be used to distinguish gastric cancer status from atrophic lesion stage." (PMID 23077637, 2012). "Our study has provided evidence that PLCε1 up-regulation might be important in the progression of gastric cancer." (PMID 23077637, 2012).
gastric cancer (continued). "Our studies also show that PLCε1 may have an important role in tumorigenesis of gastric cancer, especially at early stage, and might represent a novel marker for diagnosing early-stage gastric cancer." (PMID 23077637, 2012). "In addition, matched clinical tissues from atrophic severe gastritis and gastric cancer patients were used to further confirm the previous results by analyzing mRNA and protein levels expression of PLCε1 in clinical samples." (PMID 23077637, 2012). "The expression of PLCε1 protein in gastric cancer, normal and atrophic gastritis patients." (PMID 23077637, 2012). "The expression of PLCε1 protein in gastric cancer tissue and adjacent normal tissue." (PMID 23077637, 2012). "In addition, the sample size of the current study was relatively small, and larger study is needed to confirm the results of our present study and better clarify the implication of the genetic background of PLCE1 on the development of gastric cancer." (PMID 22412849, 2012). "Our results suggested that PLCε1 protein may be a potential biomarker to distinguish gastric cancer from inflammation lesion, and could have great potential in applications such as diagnosis and pre-warning of early-stage gastric cancer." (PMID 23077637, 2012). "Our results highly suggest that our results highly suggest that the PLCε1 protein could be a potential biomarker of gastric cancer." (PMID 23077637, 2012). "We found that PSCA rs2294008 CT/TT, PSCA rs2976392 AG/AA and PLCE1 rs2274223 AG/GG genotypes were associated with a significantly increased stomach cancer risk in a Chinese population, whereas, the MUC1 rs4072037 T>C were associated with decreased stomach cancer susceptibility." (PMID 25658482, 2015). "In this study, we examined the expression pattern of PLCε1 in human gastric tissues including normal, atrophic gastritis, and tumor tissues, and made a hypothesis on the role of PLCε1 in chronic inflammation and tumorigenesis of gastric cancer." (PMID 23077637, 2012). "Therefore, our findings support the hypothesis that potentially functional SNPs of PLCE1 may play a role in the etiology of gastric cancer." (PMID 22412849, 2012). "Thus, future studies should include more functional SNPs in PLCE1 or in other related genes in the similar biological pathways that may be involved in the etiology of gastric cancer." (PMID 22412849, 2012). "Although previous studies reported a close relationship between this SNP and enhanced risk of different cancers, we could not find a significant correlation between rs2274223 SNP in PLCE1 gene and the risk of gastric cancer, tumor characteristics, and disease stage." (PMID 31649800, 2019). "It appears that PLCE1 may not be a risk factor for all gastric cancers." (PMID 23826241, 2013). "Firstly, the mRNA and protein expression of PLCε1 were analyzed by reverse transcription-PCR and Western blotting in normal gastric mucous epithelial cell line GES-1 and gastric cancer cell lines AGS, SGC7901, and MGC803." (PMID 23077637, 2012). "Genetic variations in other genes (e.g. KDM5A, DNAH7, PLCE1, PSCA, PRKAA1, MUC1) reported to be specifically associated with gastric cancer initiation and progression were not investigated in the current study." (PMID 27929383, 2016). "The results showed both mRNA and protein levels of PLCε1 were up-regulated in gastric cancer cells compared with normal gastric mucous epithelial cells." (PMID 23077637, 2012). "We found that all gastric cancer cell lines revealed higher PLCε1 expression than that in normal gastric cell controls at both mRNA and protein levels." (PMID 23077637, 2012). "A total of 48 gastric cancer tissues and corresponding normal noncancerous tissues were subjected to the real-time PCR to quantify PLCE1 transcript levels." (PMID 22412849, 2012).
dengue (17 papers, 2013 to 2024). "We examined the associations of MICB and PLCE1 genotypes with platelet counts, as an important hematological parameter in dengue." (PMID 37958261, 2023). "This study investigated associations of variations in MICB (rs3132468) and PLCE1 (rs3740360, rs3765524) with dengue severity and thrombocytopenia in both the Indonesian and Taiwanese populations." (PMID 37958261, 2023). "Another study revealed that MICB rs3132468 and PLCE1 rs3740360 are significantly associated with clinical phenotypes of dengue less severe than DSS." (PMID 37958261, 2023). "Genetic varients in major histocompatibility complex class I polypeptide-related sequence B (MICB) and 1-phosphatidylinositol-4,5-bisphosphate phosphodiesterase epsilon-1(PLCE1) has been found to be associated with dengue." (PMID 31954402, 2020). "This study aimed to explore the functional basis of specific mutations in the MICB and PLCE1 genes previously shown to be associated with severe dengue." (PMID 28599625, 2017). "The association with mutations in PLCE1 and dengue raises the possibility of a role for this gene in the maintenance of normal endothelial integrity." (PMID 28599625, 2017). "Genetic variants of MICB and PLCE1 have also been found to be associated with less severe forms of dengue, and also dengue in infants." (PMID 26968374, 2016). "Previous association studies using cord blood controls suggest that MICB and PLCE1 SNPs are associated with not only DSS but also less severe form of dengue." (PMID 24884822, 2014). "The present study revealed that MICB and PLCE1 SNPs are associated with a progression from less severe symptom of dengue to DSS in Thai children with dengue." (PMID 24884822, 2014). "The aim of this study was to define the extent to which MICB (rs3132468) and PLCE1 (rs3740360) were associated with less severe clinical phenotypes of pediatric and adult dengue." (PMID 23536857, 2013). "We have shown that the MICB rs3132468 and PLCE1 rs3740360 genotypes are associated with clinically apparent dengue in both adults and children, which is a significant extension from the earlier GWAS on DSS cases alone." (PMID 23536857, 2013). "Similar findings of a previous study in Vietnam indicated that the functional basis of MICB and PLCE1 variants in thrombocytopenia of dengue patients remains unclear." (PMID 37958261, 2023). "Therefore, further studies with a larger sample size and more clinical information are needed to confirm the associations of MICB and PLCE1 variants with the severity of dengue." (PMID 37958261, 2023). "PLCE1 rs3765524 is associated with the susceptibility to dengue shock syndrome and may be the pathogenesis of severe dengue fever complications." (PMID 35765945, 2022). "While it is plausible that the relationship between mutations in PLCE1 and both severe dengue and nephrotic syndrome suggests some role in the maintenance of endothelial integrity, it is more difficult to relate this potential function to oesophageal malignancy." (PMID 28599625, 2017). "However, the limitation is that the possible association of MICB and PLCE1 SNPs with susceptibility to less severe form of dengue cannot be assessed, since only patients with symptomatic dengue infection are available." (PMID 24884822, 2014). "Thus this study tested the hypothesis that the MICB (rs3132468) and PLCE1 (rs3740360) variants were associated with clinically important laboratory features of dengue." (PMID 28599625, 2017). "Several genetic loci associated with dengue fever have been identified in various studies, including MICB rs3132468 and PLCE1 rs376552423." (PMID 37833411, 2023). "Our results further showed the association between MICB rs3132468 and DSS, as well as PLCE1 rs3740360 and DHF in secondary dengue among Indonesian patients." (PMID 37958261, 2023).